UTP14C (UTP14C small subunit processome component)
Description:
Essential for spermatogenesis. May be required specifically for ribosome biogenesis and hence protein synthesis during male meiosis (By similarity).
Synonyms: KIAA0266; 2700066J21Rik; UTP14B
Tractability: PROTAC: UniProt records ubiquitination sites on it; ubiquitination databases record sites on it.
Gene: Protein-coding gene on chromosome 13 (52,024,691 to 52,033,600, forward strand). Ensembl gene ENSG00000253797.
Subcellular location: Nucleus, nucleolus
Subcellular location (Human Protein Atlas): Nucleoli; Cytosol
Pathways (Reactome):
Metabolism of RNA: Major pathway of rRNA processing in the nucleolus and cytosol; rRNA modification in the nucleus and cytosol
Gene Ontology:
Molecular function: protein binding
Biological process: rRNA processing
Cellular component: small-subunit processome; nucleolus
Genetic constraint (gnomAD): Loss-of-function variants: 10 observed, 15.43 expected, observed/expected ratio (o/e) 0.65, 90% interval 0.4 to 1.1. The upper end of that interval is the gene's LOEUF score, 1.1, which puts it in group 4 of 6, group 1 being the genes least tolerant of losing a copy. Missense variants: 818 observed, 929.78 expected, observed/expected ratio (o/e) 0.88, 90% interval 0.83 to 0.93. Synonymous variants: 315 observed, 346.46 expected, observed/expected ratio (o/e) 0.91, 90% interval 0.83 to 1.
Homologues: Orthologues: chimpanzee UTP14C (99% identical), macaque UTP14C (93% identical), dog UTP14A (80% identical), mouse Utp14a (75% identical), rat Utp14a (74% identical), rat LOC102551819 (68% identical), mouse Utp14b (66% identical), tropical clawed frog utp14a (48% identical), zebrafish UTP14A (45% identical), Drosophila melanogaster CG12301 (27% identical), Caenorhabditis elegans F27C1.6 (23% identical). Paralogues in human: UTP14A (90% identical).
Diseases named in the same sentence as UTP14C in open-access papers:
UTP14C is named in the same sentence as 3 diseases in open-access papers, as found by Europe PMC text mining. Sharing a sentence is not in itself a finding about the gene and the disease. The quoted sentences say what the papers report.
male infertility (1 paper, 2022). The inability of the male to effect fertilization of an ovum after a specified period of unprotected intercourse. "Mutations in UTP14C gene have been linked to spermatogenic arrest and male infertility." (PMID 34190021, 2022).
ovarian carcinoma (1 paper, 2009). A malignant neoplasm originating from the surface ovarian epithelium. "We tested for the expression of five of the known retrogenes, UTP14C, PGK2, RPL10L, RPL39L and UBL4B in normal human ovary and ovarian cancers." (PMID 19333399, 2009). "The unexpected expression of UTP14C in the human ovary prompted us to explore whether or not UTP14C was also expressed in ovarian cancers." (PMID 19333399, 2009).
cancer (1 paper, 2023). A tumor composed of atypical neoplastic, often pleomorphic cells that invade other tissues.